ZDHHC5 (zDHHC palmitoyltransferase 5)
Description:
Palmitoyltransferase that catalyzes the addition of palmitate onto various protein substrates such as CTNND2, CD36, GSDMD, NLRP3, NOD1, NOD2, STAT3 and S1PR1 thus plays a role in various biological processes including cell adhesion, inflammation, fatty acid uptake, bacterial sensing or cardiac functions. Plays an important role in the regulation of synapse efficacy by mediating palmitoylation of delta-catenin/CTNND2, thereby increasing synaptic delivery and surface stabilization of alpha-amino-3-hydroxy-5-methyl-4-isoxazole propionic acid receptors (AMPARs). Under basal conditions, remains at the synaptic membrane through FYN-mediated phosphorylation that prevents association with endocytic proteins. Neuronal activity enhances the internalization and trafficking of DHHC5 from spines to dendritic shafts where it palmitoylates delta-catenin/CTNND2. Regulates cell adhesion at the plasma membrane by palmitoylating GOLGA7B and DSG2. Plays a role in innate immune response by mediating the palmitoylation of NOD1 and NOD2 and their proper recruitment to the bacterial entry site and phagosomes. Also participates in fatty acid uptake by palmitoylating CD36 and thereby targeting it to the plasma membrane. Upon binding of fatty acids to CD36, gets phosphorylated by LYN leading to inactivation and subsequent CD36 caveolar endocytosis. Controls oligodendrocyte development by catalyzing STAT3 palmitoylation (By similarity). Acts as a regulator of inflammatory response by mediating palmitoylation of NLRP3 and GSDMD. Palmitoylates NLRP3 to promote inflammasome assembly and activation. Activates pyroptosis by catalyzing palmitoylation of gasdermin-D (GSDMD), thereby promoting membrane translocation and pore formation of GSDMD. Palmitoylates IFT81 and may contribute to maintaining its protein stability during spermatogenesis thereby supporting proper sperm tail assembly (By similarity).
Synonyms: KIAA1748; ZNF375; DHHC5
Tractability: Antibody: UniProt places it where antibodies can reach, with high confidence; its Gene Ontology location is reachable by antibodies, with high confidence; UniProt predicts a signal peptide or a membrane-spanning region. PROTAC: ubiquitination databases record sites on it.
Gene: Protein-coding gene on chromosome 11 (57,667,433 to 57,701,190, forward strand). Ensembl gene ENSG00000156599.
Subcellular location: Cell membrane; Synapse; Golgi apparatus
Subcellular location (Human Protein Atlas): Nucleoplasm; Plasma membrane
Pathways (Reactome):
Disease: Maturation of spike protein
Gene Ontology:
Molecular function: palmitoyltransferase activity; protein binding; protein-cysteine S-palmitoyltransferase activity
Biological process: positive regulation of NLRP3 inflammasome complex assembly; positive regulation of pattern recognition receptor signaling pathway; positive regulation of protein localization to plasma membrane; positive regulation of pyroptotic inflammatory response; protein localization to plasma membrane; protein palmitoylation; spermatogenesis; positive regulation of protein localization to phagocytic vesicle; regulation of postsynaptic membrane neurotransmitter receptor levels
Cellular component: membrane; phagocytic vesicle; plasma membrane; synapse; Golgi apparatus; Golgi membrane; dendrite; GABA-ergic synapse; glutamatergic synapse; postsynapse; postsynaptic specialization, intracellular component
Genetic constraint (gnomAD): Loss-of-function variants: 22 observed, 70.86 expected, observed/expected ratio (o/e) 0.31, 90% interval 0.22 to 0.44. The upper end of that interval is the gene's LOEUF score, 0.44, which puts it in group 1 of 6, group 1 being the genes least tolerant of losing a copy. Missense variants: 746 observed, 967.52 expected, observed/expected ratio (o/e) 0.77, 90% interval 0.73 to 0.82. Synonymous variants: 313 observed, 365.94 expected, observed/expected ratio (o/e) 0.86, 90% interval 0.78 to 0.94.
Homologues: Orthologues: chimpanzee ZDHHC5 (99% identical), pig ZDHHC5 (98% identical), rat Zdhhc5 (98% identical), mouse Zdhhc5 (98% identical), rabbit ZDHHC5 (98% identical), dog ZDHHC5 (98% identical), guinea pig ZDHHC5 (94% identical), macaque ZDHHC5 (90% identical), zebrafish zdhhc5a (59% identical), zebrafish zdhhc5b (53% identical), tropical clawed frog zdhhc5 (51% identical). Paralogues in human: ZDHHC8 (49% identical).
Diseases named in the same sentence as ZDHHC5 in open-access papers:
ZDHHC5 is named in the same sentence as 47 diseases in open-access papers, as found by Europe PMC text mining. Sharing a sentence is not in itself a finding about the gene and the disease. The quoted sentences say what the papers report.
glioma (17 papers, 2019 to 2025). A benign or malignant brain and spinal cord tumor that arises from glial cells (astrocytes, oligodendrocytes, ependymal cells). "ZDHHC5 overexpression in gliomas is linked to the palmitoylation of EZH2, resulting in reduced EZH2 phosphorylation and lower H3K27me3 levels." (PMID 40180214, 2025). "Overexpression or knockdown of zDHHC5 affected cell growth, the cell cycle, self-renewal and invasiveness, and the expression level of zDHHC5 was inversely associated with the overall survival of glioma patients." (PMID 38293675, 2023). "zDHHC5 expression was also linked to stemness and malignant growth in glioma." (PMID 39429488, 2024). "Studies have shown that higher levels of ZDHHC5 correlate with decreased survival and unfavorable clinical outcomes in patients with glioma, suggesting its potential as a prognostic marker." (PMID 40180214, 2025). "A recent study revealed that ZDHHC5 increases the self-renewal capability of glioblastoma stem cells (GSCs), thereby actively contributing to the tumorigenicity of glioma cells." (PMID 38233791, 2024). "Propofol promotes glioma growth through zDHHC5 and EZH2, and tight control of Propofol dosage in the clinic leads to better prognosis for patients after surgical removal of tumors." (PMID 38293675, 2023). "For instance, studies demonstrate that ZDHHC5 participates in modifying cancer stem-like properties through interaction with EZH2—a pathway previously observed in glioma stem cells that may share conserved mechanisms with prostate cancer." (PMID 41343534, 2025). "ZDHHC5-mediated palmitoylation of EZH2 promoted tumorigenicity of glioma stem cells." (PMID 35541896, 2022).
glioma (continued). "ZDHHC5 has attracted considerable attention due to its elevated expression in tumor tissues, where it regulates key oncogenes and tumor suppressors, thus facilitating tumorigenesis and progression in various cancers, including gliomas, breast cancer, and pancreatic cancer." (PMID 40180214, 2025). "Here, these results suggest a potential pathway by which propofol activates GABAAR, leading to the upregulation of Src and subsequent upregulation of EZH2 palmitoylation mediated by ZDHHC5 and the enhancement of stem-like properties of gliomas that may promote tumor growth." (PMID 35927718, 2022). "It has been reported that ZDHHC5 may be involved in the maintenance of dryness in glioma cells." (PMID 35927718, 2022). "Both the protein level of ZDHHC5 and S-palmitoylation level of FAK were markedly elevated in glioma tissue compared to normal tissue." (PMID 38233791, 2024). "It was found that ZDHHC5, ZDHHC17, ZDHHC18, and ZDHHC23 promote cellular self‐renewal by targeting glioma stem cells, which in turn induces malignant progression of tumor cells." (PMID 37434393, 2023). "We found that propofol activates GABAAR to increase Src expression, thereby enhancing ZDHHC5-mediated palmitoylation of EZH2 and Oct4 and promoting the self-renewal and tumor-initiating capacity of glioma stem cells (GSCs)." (PMID 35927718, 2022). "Mechanistically, propofol enhances the stem-like properties of gliomas through GABAAR to increase Src expression, thereby enhancing the palmitoylation of ZDHHC5-mediated EZH2 and Oct4 expression." (PMID 35927718, 2022). "zDHHC5 knockdown disrupted FAK S‐acylation and membrane distribution, impairing proliferation and invasion of glioma cancer cells, while a catalytically inactive zDHHC5 Cys134S mutant reduced glioma xenografts growth." (PMID 39429488, 2024).
schizophrenia (6 papers, 2015 to 2023). A major psychotic disorder characterized by abnormalities in the perception or expression of reality. "Chromosomal deletions in the region including ZDHHC5 are linked with schizophrenia as well as bipolar disorder, and a de novo missense mutation in ZDHHC5 has been identified in patients with schizophrenia." (PMID 34659801, 2021). "Interestingly, a de novo mutation in Zdhhc5 has been reported in a patient with schizophrenia that introduces a premature stop codon at residue 648 (E648), resulting in the loss of the last 68 amino acids of Zdhhc5, including the PDZ-binding motif." (PMID 33758079, 2021). "We demonstrate in vitro that this is dependent on the enzymatic activity of Zdhhc5, its localization at the plasma membrane and its C-terminal domain, which has been shown to be truncated in a patient with schizophrenia." (PMID 33758079, 2021). "Two closely related PATs, ZDHHC5 and ZDHHC8, have been associated with schizophrenia." (PMID 34659801, 2021). "We chose to further study ZDHHC2 and ZDHHC5 as they have been shown to regulate activity-induced palmitoylation of synaptic proteins, as well as ZDHHC8 and ZDHHC9 as their function is disrupted in a subset of patients with schizophrenia and X-linked intellectual disability, respectively." (PMID 37039765, 2023). "A pleiotropic effect for overexpression of Zinc Finger DHHC-Type Containing 5 (ZDHHC5) on schizophrenia and MDD was also observed using blood SNP weights—schizophrenia: ZTWAS = 5.96, P = 2.49 × 10−9, MDD: ZTWAS = 4.54, P = 5.62 × 10−6." (PMID 32398653, 2020).
lung adenocarcinoma (3 papers, 2017 to 2025). A carcinoma that arises from the lung and is characterized by the presence of malignant glandular epithelial cells. "ZDHHC5 demonstrates tissue-specific oncogenicity: In lung adenocarcinoma (LUAD), ZDHHC5 overexpression correlates with tumor progression and INCENP expression." (PMID 40977744, 2025). "ZDHHC5 was previously seen involved in neoplasia with different partners: a ZDHHC5-SMTNL1 fusion was found in SCC of the ovary, a CTNND1-ZDHHC5 in adenocarcinoma of the lung, ZDHHC5-LCT in adenocarcinoma of the breast, and MEF2D-ZDHHC5 in grade III-IV astrocytoma of the brain." (PMID 28186972, 2017).
pancreatic cancer (3 papers, 2023 to 2025). "Lomitapide, an inhibitor of ZDHHC5, reduces the growth and proliferation of pancreatic cancer cells both in vitro and in mouse models." (PMID 40681504, 2025). "Lomitapide, a ZDHHC5 inhibitor, has demonstrated significant efficacy in reducing pancreatic tumor cell growth and proliferation, as validated both in vitro and in models." (PMID 40681504, 2025). "According to 177 TCGA public pancreatic cancer samples, the survival rate of ZDHHC5 (high expression, n = 45) patients is much lower than that of ZDHHC5 (low expression, n = 132) patients." (PMID 36774350, 2023). "We evaluated the antitumor effects of silencing ZDHHC5 in vitro and in vivo, confirming that ZDHHC5 is a potential target for inhibiting pancreatic cancer cell proliferation." (PMID 36774350, 2023). "Herein, we compare single-cell transcriptome data between pancreatic cancer tissues and normal pancreas tissues and identify that ZDHHC5 is a potential target to inhibit proliferation of pancreatic cancer cells." (PMID 36774350, 2023). "In conclusion, we first compared single-cell transcriptome data from pancreatic cancer and normal pancreatic tissues and found that ZDHHC5 is a potential target for inhibiting pancreatic cancer cell proliferation." (PMID 36774350, 2023). "Based on our single-cell transcriptome sequencing data, we propose that ZDHHC5 is a potential anti-pancreatic cancer target." (PMID 36774350, 2023). "Furthermore, we perform in vitro and in vivo experiments to show that knockdown ZDHHC5 significantly inhibit the proliferation of pancreatic cancer cells." (PMID 36774350, 2023). "Taken together, we hypothesized that antagonizing ZDHHC5-mediated palmitoylation on the cytoplasmic tail of SSTR5 may represent a more efficacious approach for the treatment of pancreatic cancer." (PMID 36774350, 2023). "Based on published literatures and our above results, we hypothesize that SSTR5 palmitoylated by ZDHHC5 would downregulate its inhibitory effect leading pancreatic cancer cell’s proliferation." (PMID 36774350, 2023). "In the present study, we performed single-cell transcriptome sequencing on pancreatic cancer patient samples and identified ZDHHC5 as a potential target for anti-proliferation of pancreatic cancer cells by silencing ZDHHC5 in cancer cells which results in dramatic antitumor effects." (PMID 36774350, 2023). "This is the first study, to our knowledge, to demonstrate the utility of a pharmacological inhibitor of ZDHHC5 in pancreatic cancer, representing a new class of palmitoylation targeted therapy and laying a framework for paradigm-shifting therapies targeting cancer cell palmitoylation." (PMID 36774350, 2023). "We hypothesized that antagonizing ZDHHC5-mediated palmitoylation on the cytoplasmic tail of SSTR5 may represent a more efficacious approach for the treatment of pancreatic cancer." (PMID 36774350, 2023).
Alzheimer disease (2 papers, 2025). A progressive, neurodegenerative disease characterized by loss of function and death of nerve cells in several areas of the brain leading to loss of cognitive function such as memory and language. "In the brain, ZDHHC5 is involved in synaptic plasticity, neuronal development, and circadian rhythm regulation, with dysregulation linked to neurodegenerative diseases such as Alzheimer’s disease (AD)." (PMID 40180214, 2025).
heart failure (2 papers, 2020 to 2022). Inability of the heart to pump blood at an adequate rate to meet tissue metabolic requirements. "In the present study, we evaluated changes in zDHHC5 expression in animal models of left ventricular hypertrophy and heart failure, as well as in human ischaemic heart failure samples." (PMID 36277202, 2022). "We investigated expression of zDHHC5 in animal models of left ventricular hypertrophy (LVH) and heart failure (HF), along with HF tissue from humans." (PMID 36277202, 2022).
lung carcinoma (2 papers, 2021 to 2022). "Although ZDHHC5 or palmitoylation has been linked to lung cancer, its association with CSC has not been reported." (PMID 34621750, 2021). "Furthermore, in lung cancer, although ZDHHC5 expression levels have little to do with overall survival, the inhibition of ZDHHC5 expression results in significantly decreased cell proliferation, migration, and xenograft growth." (PMID 36359005, 2022).
viral infection (2 papers, 2022). "Interestingly, we found that the ubiquitination of many host proteins that interact with SARS-CoV-2 was also changed after viral infection, such as ZDHHC5, BUD31, SCP2, ARL6IP4, and NUDCD2, which were reported to interact with the SARS-CoV-2 Spike protein." (PMID 36071039, 2022).
breast carcinoma (1 paper, 2025). "Similarly, LXR agonist T0901317 modulates ZDHHC5 and FLOT2 expression, exerting anti-proliferative effects in breast cancer cell models." (PMID 40180214, 2025).
cardiac hypertrophy (1 paper, 2022). "In contrast to cardiac hypertrophy, zDHHC5 expression was either unchanged (rabbit), modestly reduced (pig) or significantly reduced (human) in a HF setting." (PMID 36277202, 2022). "Firstly, we observed that in a LVH model of cardiac hypertrophy and remodelling, zDHHC5 expression was upregulated as early as 3 days post-onset, and this was maintained until 8 weeks post-injury." (PMID 36277202, 2022). "This study provides novel evidence that palmitoylation of cardiac substrates is altered in the setting of HF, and that expression of zDHHC5 is dysregulated in both hypertrophy and HF." (PMID 36277202, 2022).
depression (1 paper, 2021). "ZDHHC5 is a palmitoyl acyltransferase, and attenuated 5-HT1AR palmitoylation has been shown to induce depression-like behaviors." (PMID 34807913, 2021).
generalized anxiety disorder (1 paper, 2025). An anxiety disorder characterized by excessive and difficult-to-control worry about a number of life situations. "Mendelian randomization identifies palmitoylation genes driving generalized anxiety disorder (GAD) risk, notably ZDHHC5 and ZDHHC13." (PMID 40898659, 2025).
lung acinar adenocarcinoma (1 paper, 2025). "ZDHHC5 has not been implicated in brain development but has been linked to lung acinar adenocarcinoma and lung papillary adenocarcinoma in prior studies." (PMID 40360802, 2025).